EGFR (epidermal growth factor receptor)
Diseases named in the same sentence as EGFR in open-access papers (continued):
Sharing a sentence is not in itself a finding about the gene and the disease.
tumor (continued). "We combined tumour mutation data from the Cancer Genome Atlas with matched patient genetic data, and tested for germline variants that associate with somatic mutation of the EGFR pathway (including EGFR, KRAS, BRAF, PTEN and PIK3CA)." (PMID 24152305, 2013). "When only patients with confirmed EGFR mutation in tumor were analyzed, 17% (6 of 35) of them showed positive plasma EGFR mutation and the mutation type was completely matched with that in tumor." (PMID 23927790, 2013). "Various EGFR mutations are well-documented and shown to be tumor-type specific." (PMID 24349829, 2013). "Furthermore, there was a quantitative relationship - higher EGFR mRNA level was correlated with more pronounced tumor shrinkage, independently of EGFR mutational status." (PMID 24039832, 2013). "Furthermore, combination of anti-ErbB3 antibodies with EGFR TKIs synergistically affect cell proliferation in vitro, cause cell cycle arrest, up-regulate p21 expression and inhibit tumor growth in mouse xenografts." (PMID 23896512, 2013). "Tumor EGFR levels by IHC were associated with survival while EGFR levels by RPPA were not, which is speculated to be due to inherent differences in antibody and assay performance." (PMID 25587491, 2013). "However, EGFR mutation can nonetheless induce tumor formation in the presence of an apparently intact DOK2 gene." (PMID 24255704, 2013). "The authors suggested that the tumor heterogeneity reported by others was actually a pseudoheterogeneity resulting from a mutant allele-specific imbalance (MASI) or from heterogeneously distributed EGFR amplification." (PMID 23418425, 2013). "However, there are no reports in the literature investigating an association between the EGFR mutation and the stage of the tumor." (PMID 23403410, 2013). "The mutation may also aid in faster tumor growth, especially when occurring in concurrence with another EGFR-activating mutation." (PMID 23407898, 2013). "Why did tumor with low abundance of KRAS mutation tend to response to EGFR antibody therapy?" (PMID 23874486, 2013). "Additionally, studies on patient tumor sections have shown a positive correlation between EGFR activating mutations and nuclear accumulation of β-catenin in primary NSCLC." (PMID 24223799, 2013). "Although KRAS mutation has been studied for the predictive value of tumor response to anti-EGFR treatment and also has been confirmed to be the highly predictive of resistance to anti-EGFR treatment, the prognostic value of KRAS mutation in synchronous and metachronous mCRC remains controversial." (PMID 24330663, 2013). "The enhanced growth of AnxA6-deficient tumor cells on the other hand is currently believed to be driven by the high cytosolic Ca2+-induced activation of PKC isoforms that in turn activate the Ras pathway independently of EGFR activity." (PMID 24354805, 2013). "As some mutations may be present in a minor population of tumor cells, and normal cells can be mixed in tumor tissue, this highly sensitive assay can be an appropriate method for EGFR mutation analysis." (PMID 24351833, 2013). "The discovery in 2004 that activating somatic mutations in the tyrosine kinase EGFR gene make the tumor sensitive to tyrosine kinase inhibitors (TKIs) treatment has represented one of the most significant breakthrough in the field of molecular oncology in the past decade." (PMID 24376723, 2013). "Therefore, distinguishing the patients with EGFR mutation-positive tumors from those with EGFR wild-type tumours is helpful to improve clinical benefit and save money on treatment costs, which is supported by several studies." (PMID 23520448, 2013). "Intratumor heterogeneity for EGFR mutation has been proven to exist by the analysis of different areas of a single NSCLC tumor, and further evidence of this heterogeneity stems from the predictive benefit of EGFR-TKI treatment from the relative abundance of EGFR mutations." (PMID 23621919, 2013).
tumor (continued). "In addition, we found that EGFR overexpression was associated with tumor stage, as the percentage of patients with EGFR overexpression was higher in TNM stage IV than in stages I/II/III CRCs." (PMID 23865079, 2013). "We designed a highly sensitive, specific, reproducible test that detects mutations in exons 18, 19, 20, and 21 in tumor samples from patients with NSCLC to identify individuals who are most likely to respond to EGFR TKI therapy using one 5-micron tissue section." (PMID 23621958, 2013). "Surgically resected tumor specimens are the optimal DNA source for EGFR mutation detection." (PMID 24351833, 2013). "Furthermore, both agents and their combination almost completely prevented TKI-resistant tumor formation (EGFR T790M mutation) in a xenograft model." (PMID 23515752, 2013). "Given the small sample sizes obtained by routine lung cancer diagnostic procedures, tissue may already be expended after histopathological evaluation of the tumor and testing for EGFR mutation." (PMID 24205040, 2013). "Since our study was not based on a pre-selected patient cohort (with the exception of tumour tissue accessibility), this may account for the lower percentage of EGFR-mutated patients." (PMID 23892415, 2013). "An additional study on a classical protein kinase C inhibitor, revealed high potency against the mutated EGFR and significantly reduced tumor growth in an in vivo xenograft model employing an EGFR-mutant NSCLC cell line containing the EGFR c.2369C>T (T790M) mutation." (PMID 23817662, 2013). "Of the 99 tumor samples screened, 13 patients (13.1%) harbored an activating EGFR mutation, 7 patients (7.1%) were ALK positive and 65 patients (65.7%) were EGFR WT and ALK negative, and in 14 patients (14.1%) there was not enough tissue to perform a valid FISH assay for ALK." (PMID 23359795, 2013). "In conclusion, our findings suggest that certain EGFR-mutated patients may still benefit from a second-line therapy including gefitinib based on the specific mechanism underlying tumor cell resistance." (PMID 24167634, 2013). "Together with observed EGFR mutation alterations, these results suggest that repeating tumor biopsies during the course of a patient's disease may better guide the choice of therapeutic regimen." (PMID 23520442, 2013). "Heterogeneous intra-tumoral EGFR mutations and different sensitivities of EGFR mutant and wild-type tumor cells to chemotherapy may be associated with alterations in overall EGFR mutation status following chemotherapy." (PMID 23520442, 2013). "In this co-targeting setting, our data suggest that an imbalance of EGFR and Met-targeting activities in tumor samples may pose the risk of increased tumor spread." (PMID 23812422, 2013). "This may be explained by the fact that the levels of total EGFR in tumor cells are so low, that the staining of the two mutation-specific antibodies may be negative in some cases, even though they have EGFR gene mutations detected." (PMID 23536868, 2013). "Indeed, approximately 60–80% of patients whose tumor samples contain somatic mutations in the kinase domain of epidermal growth factor receptor (EGFR) gene are responsive to EGFR tyrosine kinase inhibitors (TKI) gefitinib and erlotinib." (PMID 23930206, 2013). "The results suggested that chemotherapy may reduce EGFR mutation frequencies in patients with NSCLC, a likely result of a preferential response of sub-clones with EGFR mutations in tumors with heterogeneous tumor cell populations." (PMID 23520442, 2013). "We then investigated correlations between EGFR expression and clinicopathological data from the patients and found that EGFR expression was associated with advanced tumor stage (P = 0.001), tumor lymph node metastasis (P = 0.002), and higher pathological stages (UICC 2002 and 2010, P <0.001)." (PMID 24131756, 2013).
tumor (continued). "As EGFR overexpression is associated with highly aggressive and metastatic tumor cells, EGF-SubA+PDT combination might be particularly effective against primary invasive tumors either alone or in an adjuvant setting to surgery." (PMID 23887632, 2013). "This could happen through the selection of pre-existing tumor cells expressing wild-type EGFR during EGFR-TKI treatment, similar to the effect of the T790M mutation." (PMID 24369725, 2013). "Therefore, knowledge of the EGFR and K-Ras mutation status of a patient’s tumor is likely to provide a potential strategy for selecting those patients who are likely to benefit from EGFR-targeted therapies." (PMID 23403410, 2013). "In particular, since the T790M mutation seems to be critical for acquired resistance to EGFR-TKIs, the selection of antigen loss variants as immune escape might be avoided during immunotherapy and tumor evolution." (PMID 24223798, 2013). "Although further studies will be required to define the association between EGFR expression and sensitivity of tumor cells to cetuximab, our present results suggest that our method for detecting EGFR expression with cetuximab may provide a new biomarker." (PMID 23824671, 2013). "It inhibits growth and causes regression in human tumor xenografts overexpressing EGFR." (PMID 24191959, 2013). "For example, the process that should be used to select optimal candidates who possess EGFR mutations and will experience favorable tumor response to EGFR TKIs remains unclear." (PMID 24376677, 2013). "EGFR mutation is the only independent predictor of tumor response." (PMID 24252457, 2013). "A second explanation may simply be that tumor EGFR mRNA was more susceptible to degradation by RNAse during tissue preparation compared to mucosa." (PMID 24171795, 2013). "One ESCC tumor exhibited a del745-750 type of EGFR mutation." (PMID 23426935, 2013). "Importantly, complete compliance between EGFR mutational status of 32 corresponding primary tumours and brain metastases was observed." (PMID 23892415, 2013). "Among all NSCLC patients, about 25% are estimated to harbor “activating mutations” in sequences encoding the epidermal growth factor receptor (EGFR) that causes a constitutive activation of the EGFR signaling pathway and thus provides tumor cells with an increased abnormal growth advantage." (PMID 24280348, 2013). "Here, we present the technical performance verification studies of the cobas EGFR Mutation Test, including studies of the analytic sensitivity, internal and external reproducibility, minimal tumor content, interfering substances, effects of necrosis, and cross-reactivity with other mutations." (PMID 23621958, 2013). "Furthermore, in cytology material with >1,000 tumor cells in samples from a Polish Caucasian population, there was a frequency of 10% EGFR mutations, while in samples with a minimum of 5,000 tumor cells the frequency was 12,24%." (PMID 23817662, 2013). "Re-biopsy of relapsed metastatic tumor tissue showed newly emerged somatic mutations in both the KRAS and the EGFR gene, while the tumor cells still carried the original ALK rearrangement but without signs of ALK fusion gene amplification or secondary ALK mutations." (PMID 24279718, 2013). "The tumor was positive for an EGFR exon 19 deletion mutation." (PMID 23340652, 2013). "Clinicopathologic features of the tumours included in the EGFR mutation analysis." (PMID 22952784, 2012).
tumor (continued). "In addition, using immunohistochemistry to determine the expression of vascular endothelial growth factor (VEGF) and Ki-67, we studied the tumor proliferative activity and angiogenesis in adenocarcinomas showing mERα expression and EGFR mutation." (PMID 22784503, 2012). "Our observation that KRAS/BRAF wild-type and mutated tumors had overlapping kinase activity profiles is consistent with the increasing recognition of tumor heterogeneity, reflected in disparate mutation status, as determinant of variable response to anti-EGFR antibody therapy." (PMID 23226389, 2012). "Further studies revealed that just the tumor cell with EGFR-TK mutation (L858R, del742-759) could match good response to gefitinib." (PMID 22252115, 2012). "However, clinical decision making based upon very low prevalence KRAS mutations is controversial, as it has not yet been clarified how mutation heterogeneity within CRC tumours affects outcome in patients treated with EGFR antibodies." (PMID 23173730, 2012). "However, the molecular mechanisms underlying the effect of EGF/EGFR on tumor cell migration are not completely understood to date." (PMID 22701712, 2012). "H-ras mutations are more common than K-ras mutations in HNSCC and may play an important role in tumor resistance to EGFR-targeted therapies." (PMID 22545054, 2012). "The EGFR mutated SNAI1 reactivated tumor express TWIST1, VIM and CDH2 (sample 288) suggesting that TWIST1 and SNAI1 might interact to drive full mesenchymal phenotype." (PMID 22272264, 2012). "The question of whether tumor KRAS/BRAF mutation status may be a reliable biomarker for the purpose of selecting high-risk patients to anti-EGFR therapy, however, remains elusive." (PMID 23226389, 2012). "However, it is important to note that direct sequencing was unable to detect the presence of EGFR mutations in seven tumours when mutant DNA represented ≤30% of the total DNA." (PMID 22952784, 2012). "Direct sequencing identified EGFR mutations in 21 (16%) of the analyzed tumours." (PMID 22952784, 2012). "Furthermore, elevated expression of EGFR and its ligands have been found to be associated with poor clinical prognosis in several tumor types of epithelial origin." (PMID 22830443, 2012). "Recently mathematical modeling of EGFR inhibition in metastatic colon cancer suggests that the likely number of preexisting resistance mutations make it virtually impossible for a single targeting agent to prevent tumor re-growth." (PMID 23056179, 2012). "EGFR inhibition caused death of primary and immortalized cells isolated from this tumor." (PMID 23028720, 2012). "The subsequent success of EGFR targeted therapies in recent years has been attributed to the utilization of patient selection strategies based on the study of the mutation or amplification status in tumor tissue." (PMID 22974395, 2012). "Here, we examined whether the PI3K/mTOR (both mTORC1 and mTORC2) inhibitors BEZ235 and NVP-BGT226 (BGT226) could sensitise tumor cells with EGFR overexpression or Ras mutation to radiation." (PMID 22452803, 2012). "However, the heterogeneous population of EGFr expression cannot be represented by a single equation of tumour control probability (TCP), as it is intrinsically linked to a group of tumours with identical characteristics." (PMID 22713695, 2012). "Those who have EGFR mutation-positive tumours could receive continuous erlotinib; whereas those who have wild-type tumours should discontinue erlotinib after about 28 days if they do not develop a rash because of the possibility of decreased survival." (PMID 23078958, 2012). "We identified EGFR mutations in 21 (16%) of the 136 tumours analyzed by direct sequencing." (PMID 22952784, 2012). "The genetic profile of a tumor determines its biological behavior and the EGFR and KRAS mutation status could very well influence the pattern of metastasis formation, a topic that merits further investigation." (PMID 22528563, 2012).
tumor (continued). "Both of these mutations make the tumor more sensitive to compounds that inhibit EGFR, most likely by repositioning critical residues that surround the ATP-binding cleft of the tyrosine kinase domain of the receptor, which stabilizes interactions with both ATP and its competitive inhibitors." (PMID 23144692, 2012). "The association with tumour pEGFR-IR is consistent with the hypothesis that a high activity along the EGFR-Akt signalling pathway facilitates epithelial-mesenchymal transition and thereby an adverse clinical outcome." (PMID 23133535, 2012). "Elevated expression of miR-200b, decreased miR-143 level and copy number losses may identify patients with mutated KRAS tumours who benefit from anti-EGFR therapy, whereas copy number gains in wild-type KRAS patients could predict resistance to cetuximab." (PMID 22804917, 2012). "Loss of PTEN expression has been reported to confer tumor resistance to anti-EGFR MoAbs." (PMID 22586484, 2012). "The LOD of the Therascreen EGFR Mutation Test kit was 5% for all the tumour samples." (PMID 22952784, 2012). "Expression of EGFR protein also associated with tumor stages." (PMID 22537942, 2012). "The Therascreen EGFR Mutation Test Kit was able to detect the presence of EGFR mutations when mutant DNA, relative to wild-type DNA, represented 1% of the total DNA in half of the tumours tested positive by the kit." (PMID 22952784, 2012). "A previous report relied on a CCSP-rtTA transgene to investigate how EGFR mutations in different lung cell types could influence tumor development." (PMID 23285300, 2012). "In addition, there was the result of the analysis with the Therascreen EGFR Mutation Test kit for 84 of these tumours, including 16 of the 19 tumours with mutation in EGFR previously indicated." (PMID 22952784, 2012). "The reduction in EGFR was potentially caused by necrosis or tumor cell differentiation." (PMID 22825751, 2012). "Moreover, loss of PTEN protein expression is frequently found in tumours with EGFR and HER2 overexpression." (PMID 22240798, 2012). "Despite the limitations in sample size and concomitant treatment our results indicate that patients with KRAS copy number loss might benefit from treatment with an anti-EGFR antibody although their tumour is KRAS mutated." (PMID 22804917, 2012). "These tumor types may cluster based on genetic instability, possibly introduced or associated with EGFR amplifications." (PMID 21714919, 2011). "However, as would be expected, tumours containing KRAS/BRAF mutation are refractory to the therapeutic effects of anti-EGFR antibodies." (PMID 21698197, 2011). "Based on the results of this and other trials, EGFR TKI treatment should not be confined to patients harbouring EGFR mutations, although the smaller benefit in patients with EGFR wild-type tumours should be taken into account in pharmacoeconomic analyses to guide reimbursement decisions." (PMID 21654681, 2011). "The BR.21 study reported that both groups (tumours having EGFR mutations or wild-type EGFR) derive a survival benefit from treatment with erlotinib compared with placebo, although the effect of erlotinib was much greater in patients with EGFR-mutated tumours." (PMID 21654681, 2011). "It is well known that the optimal DNA resource for EGFR mutation analysis is tumor tissue." (PMID 22142557, 2011). "We found EGFR mutation in 12 of the 71 tumour samples (17%)." (PMID 21575252, 2011). "Of the 13 tumours harbouring an EGFR mutation, all belonged to the high Gleason Score group." (PMID 21266046, 2011). "In the present study, we retrospectively examined 127 patients with OSCCs and multivariate analysis revealed that number of pathologically positive lymph nodes and presence of EGFR numerical aberrations at the primary tumours were significantly associated with ECS." (PMID 21304522, 2011). "This suggests that clonal selection within the tumor might result in EGFR mutations with differing signaling properties." (PMID 24212795, 2011).